CBL (Cbl proto-oncogene)
Diseases named in the same sentence as CBL in open-access papers (continued):
Sharing a sentence is not in itself a finding about the gene and the disease.
Moyamoya disease (3 papers, 2021 to 2022). Moyamoya disease (MMD) is a rare intracranial arteriopathy involving progressive stenosis of the cerebral vasculature located at the base of the brain causing transient ischemic attacks or strokes. "Coagulative disorders were described in patients with CBL germline mutations and in two patients with moyamoya disease." (PMID 35159106, 2022). "Other reports later described vasculopathies primarily affecting cerebral blood vessels, such as moyamoya disease in patients with germline CBL mutations." (PMID 35159106, 2022). "On the other hand, clinical indications for the investigation of CBL mutations in specific conditions, such as early-onset moyamoya disease should be provided." (PMID 35159106, 2022). "Interestingly, coagulative alterations have been reported in two patients with germline CBL mutations and Moyamoya disease." (PMID 36123612, 2022). "Moyamoya disease has also been described in patients harboring de novo CBL mutations, and in CBL syndrome without JMML." (PMID 36123612, 2022).
myocardial ischemia (3 papers, 2019 to 2025). A disorder of cardiac function caused by insufficient blood flow to the muscle tissue of the heart. "FTO inhibits NLRP3-mediated pyroptosis through the suppression of β-catenin ubiquitination and degradation by decreasing the stability of CBL mRNA, contributing to the alleviation of cardiac ischemia/reperfusion injury." (PMID 38663914, 2024). "FTO decreased the stability of Cbl Proto-Oncogene (CBL) mRNA by inhibiting m6A modification and the CBL-mediated ubiquitination and subsequent degradation of β-catenin were implicated in the suppression of pyroptosis induced by FTO during myocardial ischemia/reperfusion (I/R) injury." (PMID 39869517, 2025).
neuroblastoma (3 papers, 2018 to 2023). Neuroblastoma (NB) is the most common solid, extracranial childhood tumor. "PI3Kα inhibitor PIK-75 (78.9% cytotoxicity) stimulates anti-neuroblastoma activity by destabilizing MYCN and sensitizing tumor cells to anthracyclines, and indeed increased cytotoxicity with PIK-75 was associated with PPM1D and GNA13 gain, and DNMT3A, CBL, EED and ASXL2 loss." (PMID 34722256, 2021).
osteosarcoma (3 papers, 2014 to 2024). A usually aggressive malignant bone-forming mesenchymal neoplasm, predominantly affecting adolescents and young adults. "Ectopic c-CBL decreased the receptor tyrosine kinase levels in osteosarcomas and reduced tumor growth and metastasis by inhibiting cell proliferation, migration and invasion." (PMID 27472394, 2016). "Evidence suggests that low expression of the E3 ubiquitin ligase c-CBL protein is closely associated with high expression levels of epidermal growth factor receptor (EGFR) and platelet-derived growth factor receptor alpha (PDGFRα) in osteosarcoma tissues." (PMID 39062505, 2024).
pancreatic ductal adenocarcinoma (3 papers, 2016 to 2024). An infiltrating adenocarcinoma that arises from the epithelial cells of the pancreas. "A recent study on human pancreatic ductal adenocarcinomas validated that low c-CBL was associated with shorter survival, and had an inverse correlation with levels of epidermal growth factor receptor." (PMID 27472394, 2016). "The insufficient levels of CBL have been identified as a factor contributing to the development of chemotherapy resistance in pancreatic ductal adenocarcinoma (PDAC), which is attributed largely to the stress-induced activation of EGFR (epidermal growth factor receptor)." (PMID 39130630, 2024). "Prior studies have revealed the potential dysregulation of SRC signaling in pancreatic ductal adenocarcinoma (PDAC) due to the alterations in CBL, where CBL acts as a pivotal molecule in modulating SRC and/or PI3K/AKT signaling." (PMID 39130630, 2024).
papillary thyroid cancer (3 papers, 2021 to 2024). "The elevated CBL levels, in turn, exert an inhibitory effect on the activation of the Wnt/β-catenin signaling pathway, thus stalling the progression of papillary thyroid carcinoma (PTC)." (PMID 39130630, 2024). "Recent evidence revealed an inhibitory effect of circ-ITCH on the progression of papillary thyroid cancer via affecting the circ-ITCH/miR-22-3p/CBL axis." (PMID 34531437, 2021). "Furthermore, it was discovered that circ-ITCH plays a pivotal role in impeding the progression of papillary thyroid carcinoma (PTC) through its influence on the circ-ITCH/miR-22-3p/CBL axis." (PMID 39130630, 2024). "Moreover, recent evidence also revealed the inhibitory effect of circ-ITCH in the progression of papillary thyroid cancer via affecting the circ-ITCH/miR-22-3p/CBL axis." (PMID 34531437, 2021).
renal cell carcinoma (3 papers, 2020 to 2026). "In renal cell carcinoma (RCC), the miR-200a-3p/CBL regulatory axis is a new mechanism under pathogenesis." (PMID 32380777, 2020).
seminoma (3 papers, 2018 to 2025). A radiosensitive malignant germ cell tumor found in the testis (especially undescended), and extragonadal sites (anterior mediastinum and pineal gland). "For example, seminomas showed significantly higher frequency of 11q24.2 (CHEK1/CBL) deletions compared to non-seminomas (30% vs. 11%; Fisher’s exact test, P = 3.41e-04)." (PMID 40568177, 2025). "Association with seminoma was found for mutations in KIT, KRAS and NRAS and for putative oncogenic driver genes CBL, RAC1, PIK3CA, and CTNNB1 (analysed jointly due to lower frequency), p = 3.33 × 10−10, p = 1.41 × 10−6, p = 0.002, p = 0.009, respectively." (PMID 32366847, 2020). "CBL copy number negatively correlated with KIT protein expression for most tumors; however, seminomas with KIT or KRAS mutations maintained high protein levels of KIT regardless of CBL copies, apparently escaping CBL regulation." (PMID 29898407, 2018). "CBL, which regulates ubiquitin-mediated degradation of KIT, was deleted in 48% of KIT-WT seminomas, leaving just one copy." (PMID 29898407, 2018).
Thrombocytopenia (3 papers, 2024 to 2025). A reduction in the number of circulating thrombocytes. "The patient who died had multiple high-risk features (severe thrombocytopenia and elevated fetal hemoglobin) and acquired additional somatic mutations that included JAK3, TERT, KRAS, and CBL, and eventual transformation to AML." (PMID 39123476, 2024). "We previously established a murine model of MDS using patient-derived CBL exon 8/9 deletion (CBLΔE8/9) and RUNX1 S291 frameshift mutation (RUNX1S291fs) via BM transplantation (BMT), which showed phenotypically relevant characteristics of MDS-ineffective hematopoiesis including thrombocytopenia." (PMID 40813622, 2025).
Thrombocytosis (3 papers, 2017 to 2025). Increased numbers of platelets in the peripheral blood. "Thrombocytosis is either due to GOF alterations that activate MPL signaling (MPL, JAK2, CALR) or due to LOF mutations of negative regulators of this pathway (CBL, LNK)." (PMID 28955303, 2017).
vasculitis (3 papers, 2014 to 2024). "In summary, our cohort of patients with germline monoallelic CBL missense variants and somatic LOH presented features typical of this condition, including, in particular, vasculitis and autoantibodies." (PMID 39403923, 2024). "Some patients with CBL mutations can have aggressive JMML, while others appear to spontaneously resolve, only to go on later to develop significant, and sometimes fatal, vasculitis." (PMID 24734223, 2014). "Intriguingly, patients with germline CBL UbLOF variants and somatic LOH displaying spontaneous JMML regression may develop autoinflammation, particularly vasculitis, either during JMML or later in life." (PMID 39403923, 2024). "On the contrary, individuals with JMML and homozygous CBL mutations who undergo HSCT seem not to develop vasculitis, suggesting that a normal immune/hematopoietic system could be pivotal in preventing these manifestations." (PMID 36123612, 2022). "This vasculitis does not appear to be seen in patients who undergo HCT, such that we are still recommending HCT for patients with CBL mutations who demonstrate an aggressive clinical course, at least until we have a better understanding of why certain patients spontaneously improve." (PMID 24734223, 2014).
arterial hypertension (2 papers, 2022). "Constitutional abnormalities in CBL mutation-associated syndrome include impaired growth, developmental delays, cryptorchidism, and late-onset vascular disorders such as optic atrophy, arterial hypertension, and acquired cardiomyopathy." (PMID 35887217, 2022).
asthma (2 papers, 2021 to 2024). "This study aims to investigate the role of c-CBL in childhood asthma and Th2 differentiation, and explore the underlying mechanism." (PMID 39342146, 2024). "In the present study, we collected peripheral blood from childhood asthma cases and healthy controls, and found that c-CBL was downregulated in the CD4 + T cells from asthmatic children." (PMID 39342146, 2024). "In the present study, we found that c-CBL was lowly expressed in CD4 + T cells from peripheral blood from asthma children and OVA-challenged neonatal mice." (PMID 39342146, 2024). "c-CBL alleviated asthma and suppressed Th2 differentiation by facilitating LCK ubiquitination, interrupting c-JUN activation and CD28 expression in vivo and in vitro." (PMID 39342146, 2024). "Gain-of-function experiments were performed in mice and human CD4 + T cells to verify the role of c-CBL in asthma and Th2 development." (PMID 39342146, 2024). "The contents of an anaphylaxis marker OVA-specific IgE in BALF and blood were also elevated in asthma mice, and reduced by c-CBL." (PMID 39342146, 2024). "We collected peripheral blood samples from clinical childhood asthma cases and healthy controls, and determined c-CBL expression in CD4 + T cells." (PMID 39342146, 2024). "c-CBL/LCK/c-JUN/ETS1/CD28 axis was beneficial for asthma, and may provide novel targets for asthma therapy." (PMID 39342146, 2024). "The overexpression of c-CBL restrained OVA-challenged asthma and inhibited Th2 development in mice." (PMID 39342146, 2024). "These evidences suggested that c-CBL may be involved in asthma progress via regulating T cell differentiation." (PMID 39342146, 2024). "The results revealed that the c-CBL expression was significantly reduced in CD4 + T cells from both peripheral blood and spleen of asthma mice, which was consistent with results from asthmatic children." (PMID 39342146, 2024). "c-CBL/LCK/c-JUN/ETS1/CD28 axis was partially involved in childhood asthma, and may provide novel insights for clinical treatment for asthma." (PMID 39342146, 2024). "This suggested that the decreased expression of c-CBL may contributed to LCK function in Th2 differentiation and asthma development." (PMID 39342146, 2024).
B cell lymphomas (2 papers, 2011 to 2013). "CBL (murine Cas-Br-M) was first identified as part of a transforming retrovirus that induces mouse pre-B and pro-B cell lymphomas." (PMID 21394196, 2011).
herpesvirus infection (2 papers, 2012 to 2021). "Further56, reported that targeting CBL and lipid rafts have the potential to block Kaposi's sarcoma-associated herpesvirus infection of endothelial cells." (PMID 33968364, 2021).
lymphedema (2 papers, 2022 to 2025). Excess fluid collection in tissues, causing swelling. "Functional mutations in CBL and PTPN11 can cause NS with lymphedema." (PMID 40766782, 2025).
lymphoid neoplasm (2 papers, 2016 to 2024). A neoplasm composed of a lymphocytic cell population which is usually malignant (clonal) by molecular genetic and/or immunophenotypic analysis. "By contrast, lymphoid neoplasms are extremely rare in humans with CBL variants, and the role of CBL in their transformation is unclear." (PMID 39403923, 2024). "Mutations of c-CBL have been reported in a few myeloid and lymphoid neoplasms, and there is limited evidence suggesting that disruption of c-CBL function may contribute to the pathogenesis of other solid tumors as well." (PMID 27472394, 2016).
pancreatic cancer (2 papers, 2024 to 2025). "The Sorbin and SH3 domain containing 1 (SORBS1), a protein linked to insulin signaling CBL interaction, was investigated for its role in pancreatic cancer apoptosis." (PMID 40918460, 2025). "It was found that down-regulating CBL could significantly inhibit the formation of pancreatic cancer cells." (PMID 39130630, 2024). "In addition, the GEM implant local delivery of gemcitabine inhibits tumor cell growth by promoting c-CBL-mediated EGFR degradation, thus inhibiting the proliferation, angiogenesis, and epithelial mesenchymal metastasis of pancreatic tumor." (PMID 39130630, 2024).
periodontitis (2 papers, 2020 to 2024). An acute or chronic inflammatory process that affects the tissues that surround and support the teeth. "Notably, four of the cluster A genes, specifically, CBL, GRB2, PIK3R1, and RELA, were also ranked among the five leader genes previously identified in periodontitis." (PMID 32962181, 2020). "Moreover, a bi-directional relationship is suggested by several authors because of the increased production of pro-inflammatory cytokines such as IL1B, IL4, IL6, IL10, CBL, and RELA, which are often present in the periodontitis development and CRC carcinogenesis." (PMID 39517401, 2024).
systemic mastocytosis (2 papers, 2012 to 2025). Systemic mastocytosis (SM) comprises a heterogeneous group of rare acquired and chronic hematological malignancies that are related to an abnormal proliferation of mast cells in tissue, including bone marrow, with or without skin involvement. "Other somatic gene alterations implicated in some cases of advanced systemic mastocytosis include mutations in TET2, SRSF2, ASXL1, RUNX1, CBL, JAK2, NRAS, and KRAS." (PMID 41440762, 2025). "Interestingly, NGS analysis did not detect any mutations in all the other KIT exons analyzed nor in other genes previously reported in patients with advanced systemic mastocytosis (TET2, SRSF2, ASXL1, RUNX1, CBL, JAK2, NRAS, and KRAS)." (PMID 41440762, 2025).
thyroid cancer (2 papers, 2021 to 2024). "Apart from human study, establishing an animal model to test the involvement of circ-ITCH/miR-22-3p/CBL axis in the development of thyroid cancer is also preferred." (PMID 34531437, 2021). "Consequently, the establishment of the circ-ITCH/miR-22-3p/CBL axis signaling pathway provides a comprehensive explanation for the role of circ-ITCH in thyroid malignant tumors." (PMID 39130630, 2024).
thyroid nodule (2 papers, 2021 to 2023). A small circumscribed mass in the THYROID GLAND that can be of neoplastic growth or non-neoplastic abnormality. "Compared with the G allele, the A allele in rs4911154 contributed to the malignancy of thyroid nodules with decreased doubling time and down-regulated CBL expression." (PMID 34531437, 2021). "In addition, we compared the expression of circ-ITCH, miR-22-3p and CBL in the tissue samples from thyroid nodule patients carrying different alleles at rs4911154." (PMID 34531437, 2021). "When comparing thyroid nodule patients with the GG genotype to those with the GA and AA alleles, the expression of circ-ITCH and CBL was significantly upregulated, whereas the expression of miR-22-3p was significantly downregulated." (PMID 37370928, 2023). "The expression of circ-ITCH and CBL was remarkably elevated, while the expression of miR-22-3p was notably suppressed in the tissue samples of thyroid nodule patients carrying the GG genotype when compared with patients carrying the GA and AA alleles." (PMID 34531437, 2021).
thyroid tumor (2 papers, 2021 to 2023). A benign or malignant neoplasm affecting the thyroid gland. "A signaling pathway of circ-ITCH/miR-22-3p/CBL axis was established to explain the effect of SNP of circ-ITCH in thyroid tumor malignancy." (PMID 34531437, 2021). "In addition, a signalling pathway including miR-22-3p, CBL, and circ-ITCH was constructed to explain how circ-ITCH SNPs affect thyroid tumour malignancy." (PMID 37370928, 2023).
vascular malformation (2 papers, 2023 to 2024). A non-neoplastic disorder that is the result of defects of vascular morphogenesis. "The remaining four genes (ARAF, CBL, GNB2 and PIK3CD) have been associated with vascular malformations with “limited evidence”." (PMID 38778413, 2024). "This includes some of the genes for moyamoya phenomenon, other vascular malformations, abnormalities of coagulation including CBL, DIAPH1, CHD4, CNOT3, and SETD5." (PMID 36253534, 2023).
/T-cell lymphoma (1 paper, 2022). "It has indeed been shown that the miR-150 target gene repertoire can highly differ between different hematopoietic malignancies, e.g., MYB, FLT3, CBL and EGR2 in MLL-rearranged AML cells, and DKC1 and AKT2 in NK/T-cell lymphoma." (PMID 35205272, 2022).
acute monoblastic leukemia (1 paper, 2024). "In conclusion, we present a case of KMT2A::CBL-positive acute monoblastic leukemia with a dismal prognosis." (PMID 38643442, 2024).
alexithymia (1 paper, 2022). An agnosia that is a deficiency in understanding, processing, or describing emotions. "For PTPN11/NSML, SHOC2, CBL, and SOS2, alexithymia was more present than expected." (PMID 36012976, 2022). "Regarding psychopathology, the findings largely confirmed our hypotheses, insofar as alexithymia was significantly present in two groups, PTPN11 and SOS1, while it was credibly present in PTPN11/NSML, SHOC2, CBL, and SOS2 as well." (PMID 36012976, 2022).
arteriopathy (1 paper, 2020). "We provide a possible mechanism for the arteriopathy associated with heterozygous CBL variants." (PMID 32637631, 2020). "It is possible that additional mechanisms promoting fibroblast proliferation and migration, angiogenesis, and collateral formation are involved in CBL-mediated arteriopathy." (PMID 32637631, 2020). "We provide a possible mechanism for the observed arteriopathy through impaired CBL-mediated degradation of cell surface receptors and dysregulated intracellular RAS signaling." (PMID 32637631, 2020). "We show that impaired Cbl-mediated degradation of cell surface receptors and dysregulated intracellular signaling through the RAS-MAPK pathway may contribute to the pathogenesis of CBL-mediated arteriopathy." (PMID 32637631, 2020). "We show that impaired CBL-mediated degradation of cell surface tyrosine kinase receptors and dysregulated intracellular signaling through the RAS-MAPK pathway contribute to the pathogenesis of the observed arteriopathy." (PMID 32637631, 2020).
bone tumors (1 paper, 2019). "The CBL gene has been reported to be decreased in primary bone tumors, and ectopic CBL expression has been reported to reduce bone tumorigenesis by promoting tyrosine kinase receptor degradation." (PMID 31324852, 2019).
breast tumor (1 paper, 2016). "Consistently, it was reported that CBL blocks the tumor suppressor activity of TGF-β and enhances breast tumor formation." (PMID 27842510, 2016).
cerebrovascular disease (1 paper, 2020). "We identified heterozygous mutations in CBL in several patients presenting with cerebrovascular disease and provide an insight into how mutant Cbl could mechanistically cause this arteriopathy." (PMID 32637631, 2020).
childhood asthma (1 paper, 2024). "The correlation analysis displayed that the mRNA level of c-CBL in CD4 + T cells was negatively related with the percentage of Th2 cells in blood of asthmatic and control children, suggested that the decreased expression of c-CBL may be involved in development of childhood asthma." (PMID 39342146, 2024).
congenital heart disease (1 paper, 2014). A heart disease that is present at birth. "The de novo splicing mutation in CBL in Patient 6 implies that this patient's condition is actually a ‘RAS-opathy’, which may be consistent with her congenital heart disease." (PMID 24463883, 2014).